IL4 (interleukin 4)
Diseases named in the same sentence as IL4 in open-access papers (continued):
Sharing a sentence is not in itself a finding about the gene and the disease.
asthma (continued). "Immunoglobulin E (IgE), interleukin-5 (IL-5) and its receptors, and interleukin-4 (IL-4) receptors are used as molecular targets for clinical diagnosis of asthma; however, specific and individual differences are very large, and the clinical treatment of asthma patients is still inadequate." (PMID 36213574, 2022). "Moreover, the mixed‐granulocytic endotype, characterized by elevated levels of eosinophils and neutrophils in bronchial‐alveolar lavages, involves the induction of dual IL‐17 and IL‐4‐secreting CD4+ T‐cells in some patients with severe asthma." (PMID 35734271, 2022). "This is probably due to the increasing number of circulating Th2 memory cells with prolonged symptom duration because Th2 memory cells secrete a large number of cytokines, such as IL-4 and IL-13, which leads to the accumulation of serum IgE and eosinophils and the occurrence of asthma." (PMID 35256891, 2022). "IL-4 and IL-13 play separate pathophysiologic functions in asthma." (PMID 36483465, 2022). "Therefore, to evaluate the efficacy of SGMHD and acrid, bitter Chinese herbs in treating asthma inflammation in rats, the IgE in serum and IL-4, IL-13, SP, CGRP, and PGE2 levels in BALF were detected with an ELISA kit." (PMID 36045655, 2022). "Dupilumab might also improve antiviral immune responses in patients with T2-high asthma because IL-4 and IL-13 impaired viral-induced IFN production and TLR3 expression." (PMID 36077310, 2022). "Given the finding that phosphorylated STAT6 is the primary target for degradation upon PARP-1 inhibition, this represents a unique opportunity to target the transcription factor for degradation during asthma where the IL-4/IL-13/STAT6 pathway is upregulated especially in uncontrolled/severe disease." (PMID 36348405, 2022). "Whereas Imuno TF reduced IL-4, IL-5, and IL-13 in lung and serum of asthma mice, we tested if this agent could modulate the gene expression of allergic asthma-associated transcription factors." (PMID 36685604, 2022). "In the study on treatment of asthma, it can diminish the expression of IL-4, IL-5, IL-13, IL-17A, IgE, CCL5, and CCL11, inhibit NF-kB- and JNK-mediated inflammatory signaling, and reduce oxidative damage through decreasing the activity of ROS and increasing SOD." (PMID 36588723, 2022). "Kaempferol, a plant flavonoid, and its glycosylated derivative, kaempferol-3-O-rhamnoside (K-3-rh), have the potential for anti-inflammatory, antioxidant, and anti-asthmatic effects in an asthma model mouse by diminishing inflammatory cells, IL-4 and IL-13, TNF-α as well as IgE immunoglobulin." (PMID 35889525, 2022). "The newest mAb approved for severe asthma is the double inhibitor of both IL-4 and IL-13 dupilumab." (PMID 35330333, 2022). "However, in contrast, enhanced synthesis of pro-inflammatory cytokines in asthma, such as IL-4, IL-5, IL-13, and IL-33, can contribute towards maintaining the lean state." (PMID 35807067, 2022). "In Th2-high asthma, IL-4 and IL-13 activate B cells, which produce IgE and sensitize mast cells." (PMID 36078171, 2022). "CLCA1, IL-4, and IL-13 were highly expressed in the serum of children with asthma." (PMID 36313877, 2022). "IL-4 takes part in the development of asthma, allergic inflammation, and multiple types of cancer." (PMID 35884907, 2022). "Th2-asthma (i.e., eosinophilic asthma) is well established to play a leading role in asthma development as more than half of asthma cases have a Th2 phenotype, characterized by the secretion of high levels of IL-4, IL-5, and IL-13 by Th2 cells." (PMID 35769905, 2022). "In spite of similar tissue cellular inflammation, sputum IL‐4, IL‐5 and CCL26 were increased in T2‐high versus T2‐low asthma, and several further T2‐associated cytokines, PGD2 and LTE4, were increased in T2‐high and T2‐intermediate asthma compared with healthy controls." (PMID 35579040, 2022).
asthma (continued). "Therefore, we propose that MGMD compounds targets the IL-4 and IL-13 pathway, which in turn activate transcription factors to modulate clinical symptoms of asthma." (PMID 33968984, 2021). "Summary of randomized clinical trials assessing IL-4/13 in severe asthma." (PMID 35126131, 2021). "Among biologics, dupilumab (Dupixent), a fully human monoclonal antibody directed against the alpha subunit of the IL-4 receptor (and inhibiting IL-4 and IL-13 signalling) has been shown to be safe and effective in adolescents and adults with severe uncontrolled asthma." (PMID 34020658, 2021). "Dual IL4/IL-13 antagonists might be particularly effective for treating patients with IgG4-RD and elevated IgE levels and/or concurrent asthma." (PMID 34305927, 2021). "However, serum levels of the cytokines IL-4, IL-9, and IL-13 were reduced significantly (p < 0.01) in the evodiamine-treated group compared with the asthma group." (PMID 33577738, 2021). "IL-2 and IL-4 in combination suppress the severity of HDM-induced asthma." (PMID 33617447, 2021). "Moreover, Th2-specific cytokines levels, including IL-4, IL-5, and IL-10, were lower in P. cocos extract-administrated groups at all doses than those in the asthma control group." (PMID 33919400, 2021). "The mechanism was suspected to be that Th2 responses (including IL-4 and IL-5) and non-Th2 responses (IL-17), which were involved in the pathogenesis of asthma, might be protective against atherosclerosis and myocardial infarction." (PMID 34321496, 2021). "Therefore, while IL-4 and IL-13 are now clinically validated therapeutic targets for the treatment of asthma, there is a clear need to improve current strategies, with the goal of reaching long-term cost-effective therapeutic effects." (PMID 33976140, 2021). "Recombinant proteins of S. mansoni were associated with an increase in IL-10 and TGF-β, an increased frequency of regulatory T and B cells, and a reduction in the frequency of activated T lymphocytes that produce IL-4 and IL-13 in individuals with severe asthma and animal models." (PMID 33732246, 2021). "Dupilumab is a human monoclonal antibody that specifically blocks the alpha receptor of interleukin-4 (IL-4), inhibiting interleukin-4 and interleukin-13 signaling of these inflammatory cytokines involved in various allergic diseases, such as asthma, atopic dermatitis and rhinitis." (PMID 34202315, 2021). "A further contribution to the pathobiology of T2-high asthma is provided by other cellular elements releasing IL-4 such as T follicular helper cells (Tfh), whose differentiation in lung-draining lymph nodes is dependent on OX40L-positive dendritic cells activated by TSLP." (PMID 33922072, 2021). "In addition, children and young adults with asthma manifest Type-2 high airway inflammation that is driven predominantly by allergy, IL-4 and IL13." (PMID 34261543, 2021). "Th17- and Th2-mediated inflammatory pathways are regulated reciprocally during asthma, thus, inhibition of type 2 cytokines, such as IL-4 or IL-5, or administration of corticosteroids leads to reorganization of immune response from Th2-mediated eosinophilic to Th17-mediated neutrophilic disease." (PMID 34084159, 2021). "Allergic asthma is the most common asthma phenotype, and Th2 immunity is classically thought to be important in mediating bronchial inflammation during allergic asthma by cytokines such as IL-4, IL-5, and IL-13 produced from CD4 + Th2 cells and innate lymphoid cells." (PMID 34194525, 2021). "Pascolizumab (a humanized monoclonal antibody anti-IL-4) inhibits the interaction between IL-4 and its receptor, provoking the repression of Th2 cell differentiation, eosinophilia, and IgE up-regulation of all processes of the early phase of asthma." (PMID 34572281, 2021).
asthma (continued). "Interleukin-4 (IL-4), IL-13, and IL-5 are type 2 (Th2) cytokines that support the vital role of Th2 lymphocytes in asthma pathogenesis by reducing the release of immunoglobulin (Ig)E and eosinophil infiltration into lung tissues, which accelerate the process of allergic asthma." (PMID 34258300, 2021). "Measurement of gene expression of the most important cytokines that drive T2-inflammation, specifically IL-4, IL-5, and Il-13, in induced sputum could be applied as a reliable biomarker for the identification of T2-high asthma." (PMID 33513844, 2021). "These cytokines are important in asthma: IL-13 and IL-4 promote antibody class switching to IgE in B cells, IL-13 can also act on smooth airway muscle cells, causing bronchoconstriction and aiding in the remodeling of airways, and IL-5 stimulates the production of eosinophil." (PMID 34831860, 2021). "It is of great interest to know whether AIT affects Tfh or Breg cells in relation to the levels of IL-4 and IL-10 in a murine asthma model." (PMID 34804031, 2021). "Indeed, we now are at a point of tremendous excitement where blockade of IL-4 and IL-13 is effective in the treatment of allergic inflammatory responses, including atopic dermatitis and moderate to severe asthma." (PMID 34557875, 2021). "For instance, Xia et al25 reported that interleukin 4 could aggravate asthma through activation the autophagy in pulmonary B cells via regulating mTOR signalling and Ptdlns3K signalling." (PMID 34050597, 2021). "Bronchial epithelium from patients with asthma has been shown to exhibit an irregular ZO-1 and occludin staining pattern and reduced barrier function that is further compromised by exposure to the Th2 cytokines IL-4 and IL-1334,35." (PMID 33790367, 2021). "Thus, it blocks the signaling from IL-4 and IL-13, which are essential cytokines in the Th2 pathways and of paramount importance in atopic diseases, including atopic dermatitis and asthma." (PMID 34041207, 2021). "Recent studies suggest that eosinophil-derived IL-13 may play a more prominent role than IL-4 in the establishment of allergic inflammation in mice models of asthma." (PMID 34829186, 2021). "An explanation for this may be that the blockade of IL-13 alone is inadequate to achieve asthma control due to overlapping roles with IL-4." (PMID 33669458, 2021). "It is located on chromosome 5q31 within the T helper 2 (Th2)-cytokine locus including IL-5, IL-4, IL-13, and it could contribute to tissue-specific Th2 inflammation in asthma and allergic diseases." (PMID 33925009, 2021). "Besides, IL-4 and IL-6 secreted by Th2 cells directly induce the generation of asthma-specific lgG1 and lgE, thus intensifying Th2 differentiation and regulating Th1/Th2 dynamic balance." (PMID 34630778, 2021). "Notably, a manifestation of disease symptoms considered extensively as hallmarks of asthma is directly or indirectly related to the overproduction of IL-4, IL-5, and IL-13." (PMID 33649900, 2021). "Dupilumab is the first dual IL-4/IL-13 biologic approved for asthma treatment." (PMID 35126131, 2021). "T helper 2 cells (Th2 cells) and type 2 cytokines (e.g., IL-4, -5 and -13) promote airway eosinophilia, bronchial hyperresponsiveness, mucus overproduction, airway remodeling and immunogloubulin E (IgE) synthesis in asthma." (PMID 34635022, 2021). "In addition, since a previous study indicated that IL‐13 contributes more strongly to the pathogenesis of arising asthma than does IL‐4,43 we used IL‐13 instead of IL‐4 for the rest of the experiments." (PMID 33534941, 2021). "Similarly, the prednisolone positive control group also showed reduced levels of IL-4, IL-5, and IL-10 compared to the asthma group." (PMID 33919400, 2021). "The pathogenesis of asthma is predominantly attributed to the excessive immune response of T helper cell type 2 (Th2) and the production of substantial amounts of inflammatory cytokines [interleukin 4 (IL-4), IL-5, and IL-13]." (PMID 34737744, 2021).
asthma (continued). "The absence of miR-155 can promote the differentiation of T cells into Th2 by increasing IL-4 secretion, but prevent the activation of Th2 triggered by dendritic cells in vivo, which may be helpful for the investigation of asthma treatment." (PMID 34635022, 2021). "A previous study showed that in utero exposures of C57BL/6 mice to 50mg/m3 of cigarette smoke led to exacerbated HDM-induced asthma in terms of increases in airway resistance, eosinophilic inflammation, and Il-4, Il-5, and IgE levels when compared to filtered-air controls." (PMID 34912233, 2021). "Moreover, we found the concentrations of IL-4, IL-5, and IL-13 were increased 4.71-fold, 3.58-fold and 3.42-fold in serum samples of asthma patients compared to healthy controls, respectively." (PMID 34749662, 2021). "The targeting of both IL-4 and IL-13 has been postulated as a novel treatment for asthma." (PMID 33669458, 2021). "In 2000, Graham14 and others proposed for the first time that children with bronchiolitis are prone to develop asthma, which may be related to the hyper-function of Th2-derived cytokines (interleukin-4 (IL-4), IL-5, and IL-13)." (PMID 33514798, 2021). "Researchers studied the relationship between body mass index (BMI) and changes in testosterone/cortisol ratio, serum IL-4/IFN-γ ratio (Th1/Th2 balance) in women with asthma, and to assess changes in cortisol, testosterone, estrogen, and progesterone levels after aerobic exercise training." (PMID 35003073, 2021). "Our data suggest that AHR may be more dependent on IL-13 than IL-4 in this chronic asthma model, and can be prevented upon prophylactic dual vaccination against IL-4 and IL-13." (PMID 33976140, 2021). "Towards this end, we retrieved four data sets of a murine model of ovalbumin‐induced asthma and four data sets of IL‐4‐stimulated or IL‐13‐stimulated bronchial epithelial cells from the GEO database as well as one data set from a previously published murine asthma model." (PMID 33960626, 2021). "Interleukin (IL)-4, IL-13, IL-5, and Th2 cytokines have a significant role in asthma development." (PMID 35046828, 2021). "This study aimed to determine whether induced sputum samples can be used for gene expression profiling of T2-high asthma classified by IL4, IL5, and IL13 expression." (PMID 33513844, 2021). "It is possible that the risk of one SNP involved in the IL-4/IL-13 pathway was not sufficient to result in profound changes in asthma susceptibility, just as our genetic associations have shown." (PMID 33810791, 2021). "Interleukin 4 (IL-4) and IL-13 regulate Th2 cell proliferation and B cell production of allergen-specific IgE, while IL-5 drives eosinophilic inflammation, all key features of the allergic responses in asthma." (PMID 35387008, 2021). "Administration of anti-IL-25 and anti-TSLP antibodies during ovalbumin-induced asthma could reduce the infiltration of inflammatory cells into airways, as well as local expression of IL-4, IL-5 and IL-13." (PMID 34084159, 2021). "In contrast, neither IL-4 nor IL-13 sputum levels were found associated with BMI in asthma patients." (PMID 33418879, 2021). "Moreover, it is noteworthy that IL-9 which is a Type II cytokine behaved differently from other Type II cytokines (IL-4, IL-5, and IL-13) and was associated with an increase in ACE2 expression in sputum of asthma patients." (PMID 35111161, 2021). "Additionally, TFH cells predominantly produce IL-2, IL-4 and IL-21 in B cell follicles and closely regulate antibody class-switching in severe inflammatory and allergic diseases, including AD, asthma, and COVID-19-induced airway inflammation." (PMID 34531749, 2021). "IL-4 has a pivotal role in asthma Th2-mediated inflammation and its functions are mediated by the interaction with two receptors: IL-4R type I (composed of the IL-4Rα and the common cytokine receptor γc-chains) and type II (composed of the IL-4Rα and IL-13Rα1 chains)." (PMID 33925009, 2021).
asthma (continued). "ELISA confirmed that IL-4/IL-17 was overexpressed in asthma/differentiation cells." (PMID 34394777, 2021). "IL13, IL4, IL4RA, FCER1B and ADRB2 are susceptible genes of asthma and atopy." (PMID 34243801, 2021). "Incidentally, asthma is characterized by increased Th2 cytokine production; however, in this model, Th2 cytokines, including IL-4, IL-5, and IL-13, which were upregulated in the HDM group, were not further upregulated in the HDM/RSV group at the mRNA and protein level." (PMID 34703996, 2021). "Suppression of Notch1 expression by HAT inhibitors reduced Th2 cytokines, especially IL-4, IL-5, and IL-13, and it may provide a therapeutic alternative for asthma." (PMID 34566492, 2021). "IL-4 is essential for the allergic response and immunoglobin E (IgE) production, and IL-5 is important for eosinophil survival and expansion, which contribute to lung injury in asthma." (PMID 33806085, 2021). "Being a key cytokine in asthma pathogenesis, the observed VitD-induced suppression of IL-4 levels may significantly contribute to the efficiency of VitD in controlling asthma pathogenesis." (PMID 34395637, 2021). "However, patients that have asthma are found to secrete IL-4, along with the generation of a TH2-polarized adaptive response." (PMID 32545470, 2020). "Thus, IL-4 and IL-13 are factors that aggravate the inflammatory response in asthma, and there are also many studies that have achieved control of Th2-type asthma by preparing IL-4 and IL-13 antibodies." (PMID 33192556, 2020). "Therefore, IL-4/STAT6 signaling plays a central role in the participation of mast cells in asthma progression." (PMID 33228696, 2020). "Therefore, further studies are required to improve our knowledge about the role of IL-4-induced macrophages in allergic asthma, through precisive elucidation of the roles of specific M2a proteins in the pathogenesis of asthma." (PMID 32024540, 2020). "The cytokines of IL-4, IL-5, and IL-13 produced by Th2 cells are deeply involved in IgE synthesis, eosinophil activation, mucus secretion, and airway remodeling during the pathogenesis of asthma." (PMID 33192556, 2020). "The IL-4 C33T single nucleotide polymorphism (rs2070874) which is located on the untranslated region (UTR) has been represented to be linked with elevated serum IgE levels and risk of asthma." (PMID 33228581, 2020). "Furthermore, they possess IgG and IgE receptors on their surface and are capable of secreting cytokines related with TH2 cell expansion, such as IL-2, IL-4, IL-5, IL-6, and IL-13, as well as various prostaglandins that are involved in asthma exacerbation." (PMID 32545470, 2020). "The preventive effects of N. sativa extract (1.25 and 2.50 g/L, p.o.)on guinea pigs OVA-induced asthma significantly decreased the levels of IL-4 and pathological changes, including intra-alveolar hemorrhage and inflammatory cells of the lung, but increased IFN-γ." (PMID 33062002, 2020). "IL-4 and IL-13 play a central role in the pathophysiology of asthma and could be very promising and appropriate targets for specific and effective new therapies." (PMID 32019141, 2020). "STAT6 is activated by IL-4 and IL-13 and plays a predominant role in the immune system including clearance of helminthic parasites as well as the pathogenesis of allergic disorders like asthma, food allergies, and atopic dermatitis." (PMID 32431691, 2020). "For example, inhibition of stearoyl-coenzyme A desaturase (SCD) in mice contributed to the development of airway hyperresponsiveness, while SCD1 gene expression was suppressed in bronchial epithelial cells in patients with asthma due to the effects of IL-4 and IL-13." (PMID 32395125, 2020). "In the Mexican-mestizo population, SNPs neither CNVs in IL4 nor IL13 are associated with asthma susceptibility or involved in plasma cytokine levels." (PMID 32366038, 2020).